SYNJ2BP (synaptojanin 2 binding protein)
Description:
Regulates endocytosis of activin type 2 receptor kinases through the Ral/RALBP1-dependent pathway and may be involved in suppression of activin-induced signal transduction.
Synonyms: OMP25; Arip2
Tractability: Antibody: UniProt predicts a signal peptide or a membrane-spanning region. PROTAC: ubiquitination databases record sites on it; its protein half-life has been measured.
Gene: Protein-coding gene on chromosome 14 (70,366,499 to 70,417,097, reverse strand). Ensembl gene ENSG00000213463.
Subcellular location: Mitochondrion outer membrane
Subcellular location (Human Protein Atlas): Mitochondria
Gene Ontology:
Molecular function: protein binding
Biological process: negative regulation of angiogenesis; negative regulation of endothelial cell migration; negative regulation of endothelial cell proliferation; negative regulation of ERK1 and ERK2 cascade; negative regulation of sprouting angiogenesis; regulation of Notch signaling pathway
Cellular component: mitochondrial outer membrane; mitochondrion
Genetic constraint (gnomAD): Loss-of-function variants: 10 observed, 16.3 expected, observed/expected ratio (o/e) 0.61, 90% interval 0.38 to 1.04. The upper end of that interval is the gene's LOEUF score, 1.04, which puts it in group 4 of 6, group 1 being the genes least tolerant of losing a copy. Missense variants: 162 observed, 189.89 expected, observed/expected ratio (o/e) 0.85, 90% interval 0.75 to 0.97. Synonymous variants: 54 observed, 69.51 expected, observed/expected ratio (o/e) 0.78, 90% interval 0.62 to 0.97.
Homologues: Orthologues: chimpanzee SYNJ2BP (100% identical), dog SYNJ2BP (93% identical), mouse Synj2bp (91% identical), guinea pig SYNJ2BP (90% identical), rat Synj2bp (89% identical), pig SYNJ2BP (79% identical), macaque COX16 (72% identical), tropical clawed frog synj2bp (56% identical), zebrafish synj2bp (53% identical). Paralogues in human: KIAA1614 (23% identical), COX16 (10% identical).
Diseases named in the same sentence as SYNJ2BP in open-access papers:
SYNJ2BP is named in the same sentence as 14 diseases in open-access papers, as found by Europe PMC text mining. Sharing a sentence is not in itself a finding about the gene and the disease. The quoted sentences say what the papers report.
breast carcinoma (5 papers, 2017 to 2025). "In breast cancer, SUMOylation of the fusion protein Synaptojanin 2 binding protein-Cytochrome-c oxidase 16 (SYNJ2BP-COX16) promotes tumor progression via phosphorylating DRP1 and increasing mitochondrial fission." (PMID 41502520, 2025). "SYNJ2BP plays a pivotal role in vesicular trafficking and the recycling of membrane protein and cellular motility, particularly in breast cancer metastasis." (PMID 29163781, 2017). "This suggested that SYNJ2BP plays an important role in the regulation of cell morphology and the progression of breast cancer." (PMID 29163781, 2017). "SYNJ2BP was able to directly regulate GSK3β phosphorylation by influencing the PI3K/AKT pathway to enhance breast cancer cell metastasis." (PMID 29163781, 2017). "To determine the relevance of SYNJ2BP function in the progression of breast cancer, we investigated the expression of SYNJ2BP in four different human breast cancer cell lines." (PMID 29163781, 2017). "IHC analysis showed that SYNJ2BP expression was significantly different when compared between normal and breast carcinoma tissues." (PMID 29163781, 2017). "To further confirm the crucial role of SYNJ2BP in EMT in breast cancer cells we expressed shRNA (shSYNJ2BP#1, #2, and #3) to reduce the expression of SYNJ2BP in MCF-7 and MDA-MB-231 cells and examined the expression level of epithelial and mesenchymal markers." (PMID 29163781, 2017). "In the present study, we found that SYNJ2BP regulated the EMT phenotype to promote breast cancer cell metastasis, and thus identified a key mechanism of tumor metastasis." (PMID 29163781, 2017). "According to IHC score, SYNJ2BP was expressed at higher levels in breast cancer tissues than in normal breast tissues, and a t-test identified a significant difference between the two groups (p = 0.0031)." (PMID 29163781, 2017). "SYNJ2BP also plays an important role in breast cancer and renal cell carcinoma metastasis." (PMID 31815134, 2019). "Particularly strong SYNJ2BP expression was observed in high grade breast carcinomas (p < 0.0001), suggesting that SYNJ2BP could promote the migration and invasion of breast cancer cells." (PMID 29163781, 2017). "The present study demonstrated that the level of SYNJ2BP expression may be used as an indicator to distinguish between breast carcinomas and normal tissues, since it was found to correlate with breast carcinoma progression in breast tumor samples." (PMID 29163781, 2017). "Our data thus identified a potential tumorigenesis role for SYNJ2BP in breast cancer." (PMID 29163781, 2017). "Taken together, these data showed that SYNJ2BP could enhance breast cancer cell metastasis in an animal model, and that SYNJ2BP could act as a crucial factor in the promotion of breast cancer cell metastasis." (PMID 29163781, 2017). "The overexpression of SYNJ2BP in breast cancer cell lines induced cytoskeletal rearrangement in the whole cell, reducing cell-cell contact and by promoting cell migration and EMT, suggesting that SYNJ2BP changed the cell EMT phenotype to promote breast cancer cell motility, migration and invasion." (PMID 29163781, 2017). "Furthermore, Pearson's correlation analysis identified a positive correlation between SYNJ2BP and the tumor stage of breast cancer (r = 0.8565)." (PMID 29163781, 2017). "SYNJ2BP plays an important role in breast cancer metastasis." (PMID 29163781, 2017). "Therefore, SYNJ2BP plays different functions in breast cancer and hepatocellular carcinoma." (PMID 29163781, 2017). "In breast cancer cells, SYNJ2BP-COX16 (a readthrough of synaptojanin 2 binding protein and COX16) SUMOylation regulates mitochondrial morphology through DRP1 SUMOylation and DRP1 phosphorylation at S616." (PMID 37627290, 2023). "In order to determine the clinical significance of SYNJ2BP in breast cancer patients, we analyzed the expression levels of SYNJ2BP in 5 normal (non-tumor) human breast tissues and 39 breast carcinoma tissues by immunohistochemical (IHC) staining." (PMID 29163781, 2017).
breast carcinoma (continued). "Moreover, a significant (p < 0.005) correlation between SYNJ2BP and p-AKT was also observed in SNAI1-positive breast cancer tissue samples." (PMID 29163781, 2017). "Collectively, our data identified a tumor inducer, SYNJ2BP, which could activate the PI3K/AKT/GSK3β/SNAI1 signaling pathway through the lysosome-mediated degradation of PTEN, and promote both EMT and tumor metastasis during the progression of breast cancer." (PMID 29163781, 2017). "In addition, SYNJ2BP was highly expressed in breast carcinoma (p = 0.0031), but not in normal breast tissue, while analysis of tissue samples taken from SNAI1-positive human breast cancers showed a significant correlation between the expression of SYNJ2BP and that of p-AKT (p < 0.005)." (PMID 29163781, 2017).
hepatocellular carcinoma (3 papers, 2016 to 2019). A malignant tumor that arises from hepatocytes. "All these results suggest that SYNJ2BP suppresses tumor growth and metastasis by targeting Notch signaling in hepatocellular carcinoma." (PMID 27440153, 2016). "However, the activity of SYNJ2BP in hepatocellular carcinoma (HCC) has not been elucidated yet." (PMID 27440153, 2016).
breast tumors (2 papers, 2017 to 2020). "Accordingly, the level of SYNJ2BP expression was positively correlated with the development of breast tumors." (PMID 29163781, 2017). "Synaptojanin 2 binding protein (SYNJ2BP) is the protein that is highly expressed in breast tumors." (PMID 32212786, 2020). "In this study, SYNJ2BP was shown to enhance breast tumor metastasis and EMT by activating SNAI1." (PMID 29163781, 2017). "The expression of SYNJ2BP was low in normal breast tissues, but increased in breast tumor tissues." (PMID 29163781, 2017).
Alzheimer disease (1 paper, 2025). A progressive, neurodegenerative disease characterized by loss of function and death of nerve cells in several areas of the brain leading to loss of cognitive function such as memory and language. "Consequently, these two genes were excluded, leaving six critical genes with diagnostic significance for Alzheimer’s disease (AD): ACO2, CS, MRPS27, SDHA, SLC25A20, and SYNJ2BP." (PMID 39757625, 2025).
motor neuron disease (1 paper, 2022). "This possibility emerges from immunoblot analysis data showing a 40% increase in Synj2bp in obese livers and a twofold increase in spinal cord tissue from patients with motor neuron disease." (PMID 36457006, 2022). "However, this might not be the case in pathophysiological conditions because the amount of Synj2bp mRNA is fourfold higher in the post-mortem spinal cord tissue of patients with motor neuron disease than in healthy individuals." (PMID 36457006, 2022).
mucinous adenocarcinoma (1 paper, 2017). An invasive adenocarcinoma composed of malignant glandular cells which contain intracytoplasmic mucin. "In a previous study, Li found that SYNJ2BP was expressed more frequently in mucinous adenocarcinoma." (PMID 29163781, 2017).
viral diseases (1 paper, 2024). "Interestingly, it has recently been reported that SYNJ2BP-dependant MERCs are involved in the physiopathology of neuronal and viral diseases." (PMID 37931956, 2024).
cancer (5 papers, 2016 to 2025). A tumor composed of atypical neoplastic, often pleomorphic cells that invade other tissues. "SYNJ2BP expression is much more frequent in malignant breast carcinoma, and may play an important role in the progression of cancer, However, little is known about the precise mechanisms underlying the effect of SYNJ2BP expression in tumor metastasis." (PMID 29163781, 2017). "The increase in SYNJ2BP expression was shown to promote the degradation of PTEN leading to cancer cell metastasis." (PMID 32212786, 2020). "This implied that the metastasis of cancer cells from the lung was a consequence of SYNJ2BP overexpression." (PMID 29163781, 2017). "This not only demonstrated a novel degradation mechanism for PTEN by the SYNJ2BP-mediated pathway, but also provided new insights into the mechanisms of cancer and highlighted a new potential target for clinical detection." (PMID 29163781, 2017). "Previous studies show that SYNJ2BP participates in sprouting angiogenesis, which plays an important part in several abnormal conditions including cancer." (PMID 27440153, 2016). "This suggests that SYNJ2 expression may coincide with phosphorylation of SYNJ2BP in cancer." (PMID 38504131, 2024). "This suggests that SYNJ2BP may play an important role in cancer progression." (PMID 29163781, 2017). "These included multitrait colocalization at 6 loci with a consistent direction of effect between CAD and cancer (ABO, PGAP3, ANGPTL4, SREBF1, HAUS6, and SYNJ2BP) and 7 with an opposing direction (CDKN1A, RGS19, CALCRL, SF3A3, LAMC1, MYO9B, and MIA3)." (PMID 40874306, 2025). "To investigate the mechanisms by which SYNJ2BP suppresses HCC growth and metastasis, we firstly adopted the Cignal Finder Cancer 10-Pathway Reporter Array to explore signaling pathways involved in this process." (PMID 27440153, 2016).
tumor (5 papers, 2016 to 2025). "In this study, we investigated the role of SYNJ2BP in tumor metastasis and established the associated underlying mechanism." (PMID 29163781, 2017). "The subsequent analysis showed that low expression of SYNJ2BP was associated with tumor size, tumor nodule number, vascular invasion, TNM stage and BCLC stage, and was an independent risk factor for survival of HCC." (PMID 27440153, 2016). "As poor prognosis of HCC is mainly due to tumor growth and metastasis, we naturally associated SYNJ2BP with HCC metastasis and growth." (PMID 27440153, 2016). "SYNJ2BP has also been reported as a negative regulator of angiogenesis and an inhibitor of tumor growth and metastasis." (PMID 28441135, 2017). "In mice that were injected with 4T1 cells that overexpressed SYNJ2BP, multiple local tumor growths of densely clustered tumor cells were seen in the lung, which significantly increased tumor infiltration into the metastatic lesions from the 5th day." (PMID 29163781, 2017). "On the other hand, SYNJ2BP owns a PDZ domain through which it interacts with ActRIIs to reduce activin to inhibit tumor growth." (PMID 27440153, 2016). "Later, the in vitro experiments demonstrated that SYNJ2BP inhibited HCC cells invasion, migration and proliferation, also the in vivo testing revealed that SYNJ2BP inhibited tumor growth and metastasis." (PMID 27440153, 2016). "Intra-tumoral SYNJ2BP levels increased gradually with tumor progression from TNM stage I to IV." (PMID 29163781, 2017). "Interestingly, 6 out of the 39 (15%) tumors showed very high (> 6) SYNJ2BP immunoreactive scores, which were closely related to tumor progression from TNM stage IV." (PMID 29163781, 2017). "SYNJ2BP suppressed stretch of F-actin, while knock down of SYNJ2BP leaded to formation of stress fiber-like structures, cell cytoskeletal and motility changes is closely related to tumor metastasis." (PMID 27440153, 2016). "Collectively, our data provide evidence that SYNJ2BP may act as a tumor suppressor during HCC development and could serve as a potential therapeutic target." (PMID 27440153, 2016). "Accordingly SYNJ2BP highly likely acts as a tumor suppressor in HCC development." (PMID 27440153, 2016). "We hypothesize that SYNJ2BP sustains DLL4 to suppress tumor growth and metastasis in human HCC." (PMID 27440153, 2016). "Reduction of Activin signaling mediated by SYNJ2BP suggested that SYNJ2BP may affect EMT through Notch, PI3K or the Activin signaling pathway in different types of tumor." (PMID 29163781, 2017). "For the reason that SYNJ2BP was down-regulated in HCC tissues and HCC cell lines, we naturally hypothesized that up-regulation of SYNJ2BP might inhibit HCC development and may act as a tumor suppressor." (PMID 27440153, 2016).
SYNJ2BP also shares sentences with these, for which no sentence is quoted: brucellosis (19 papers); infection (14); fibrosarcoma (1); neuroblastoma (1); renal cell carcinoma (1).